BRCA1 (BRCA1 DNA repair associated)
Diseases named in the same sentence as BRCA1 in open-access papers (continued):
Sharing a sentence is not in itself a finding about the gene and the disease.
cancer (continued). "After detecting a BRCA1/2 pathogenetic variant, an active surveillance is proposed and, alternatively, preventive surgery (prophylactic bilateral salpingo-ophorectomy or mastectomy) or chemoprevention to reduce cancer risk." (PMID 35661074, 2022). "Thus, a BETi can be used to “episensitize” UC cells to cytotoxic chemotherapy and inhibitors of DNA repair by inducing BRCAness in non BRCA1/2 mutated cancers." (PMID 33803654, 2021). "Women with a germline pathogenic variant in BRCA1 have a lifetime cancer risk of 70%." (PMID 34283078, 2021). "In this report, we used p18, Brca1, and Gata3 singly and doubly deficient mouse models as well as human BRCA1 proficient and deficient cancer cells to determine the mechanisms underlying the role of BRCA1 in the regulation of GATA3 in mammary tumorigenesis and metastasis." (PMID 34373738, 2021). "Multivariate logistic regression model in all carriers revealed that age at diagnosis (p =0.047), positive lymph node involvement (p = 0.05), family history of any cancer (p = 0.051, borderline) remained statistically independent predictors for BRCA1/2 mutations." (PMID 34206661, 2021). "In human breast tumours deficient for BRCA1, a significant decrease in the repression of satellite DNA was reported, where the increased satellite DNA expression promoted genomic instability and cancer progression." (PMID 34222870, 2021). "Moreover, prolonged SP18–28 treatment causes hypersensitivity to DNA-damaging agents and selectively reduces the viability of BRCA1-mutated cancer cell lines." (PMID 33608267, 2021). "Importantly, we also found that pharmaceutical inhibition of Pdgfrβ and its downstream target Pkcα suppressed Brca1-deficient tumor initiation and progression and effectively killed BRCA1-deficient cancer cells." (PMID 33478572, 2021). "Group in-person education sessions satisfied the need amongst BRCA1/2 carriers in terms of accessing necessary information regarding cancer risk assessment and management; however, the impact of group education sessions on psychological outcomes was variable across the included studies." (PMID 33804884, 2021). "Further research is required to determine their efficacy in the delay or prevention of cancer onset in the carriers of germline BRCA1/BRCA2 variants, as well as to investigate their potential toxicity, risk of secondary cancer development and any mechanisms of resistance." (PMID 34771713, 2021). "Therefore, the authors conclude that BRCA1 deficiency in tumor stroma metabolically promotes cancer progression via ketone production." (PMID 33540843, 2021). "Mutations in the BRCT domains of BRCA1 have been detected frequently in cancer patients." (PMID 33755171, 2021). "Moreover, the B,D-bilactam ASA-B and the B-lactam ASA-A steroid alkylators instigated higher increases of PARP1 mRNA cellular content in the UWB1.289 + BRCA1 than in BRCA1 mutated UWB1.289 cancer cells." (PMID 34440232, 2021). "Interestingly, this new combination strategy is likely more effective in BRCA2 deficient and BRCA proficient cancers than BRCA1-related cancers." (PMID 33589588, 2021). "RAD51 assay performed in clinical practice on tumor tissue samples may improve patient selection for PARPi therapy in non-BRCA1/2-related cancers, which likewise present HR deficiency." (PMID 33562741, 2021). "As regards therapeutic implications, ATM aberrations may sensitize cancer cells to platinum-derived drugs, similarly to the effect of BRCA1 mutations, but have a worse effect in case of radiotherapy (RT)." (PMID 34068084, 2021). "This raises the possibility that lowering the blood arsenic level by dietary means might reduce cancer risk for BRCA1 mutation carriers." (PMID 34283078, 2021). "In our study, a PABC patient carried a VUS in BRIP1 (BRCA1 interacting protein C-terminal helicase 1) which is a gene that contributes to the DNA repair function of BRCA1; the impact of this variant on molecular function and subsequent roles in cancer risk is uncertain." (PMID 34011307, 2021).
cancer (continued). "Two breakthrough studies in preclinical models demonstrated the effectiveness of PARPi in the treatment of these cancers by showing synthetic lethality between the PARPi and the mutations in BRCA1/2 encoding components of homologous recombination-mediated DNA repair (HRR) pathways." (PMID 33742140, 2021). "The observed weaker effect of arsenic exposure on cancer risk in BRCA1 mutation carriers, compared to our earlier work on those who did not inherit mutations, may be due to a difference in mean age at the blood draw." (PMID 34283078, 2021). "Thus, cancer associated BRCA1 missense variants C61G and M1775R showed a decreased recombination after MMS-treatment providing further evidence that human BRCA1 can interfere with yeast DNA repair." (PMID 34395585, 2021). "One potential strategy is inhibiting TONSL in BRCA1/2 deficient cancer, similar to PARPi." (PMID 33498235, 2021). "Thus, our results agree with previous reports on distinctive mechanisms associated with the dysfunction of BRCA1 or BRCA2 in cancers." (PMID 33525353, 2021). "Indeed, deleterious CNVs in cancer patients have been observed in more than 30% of highly penetrant cancer-predisposing genes, including BRCA1, BRCA2, APC, as well as mismatch repair (MMR) genes." (PMID 33503040, 2021). "Also, BRCA1 germline mutations account for most known heritable forms of cancer such as hereditary breast and ovarian cancer (HBOC) syndrome." (PMID 34298653, 2021). "Furthermore, PLX induced changes that render UC cells highly sensitive to the PARP inhibitor talazoparib, allowing for the extension of PARPi efficacy to non-BRCA1/2 mutated cancers." (PMID 33803654, 2021). "Therefore, the loss of BRCA1 function linked to high HMMR expression can contribute to cancer progression." (PMID 34965417, 2021). "Therefore, cancers with loss‐of function mutations in HR pathway components such as BRCA1, ATM, ATR, RAD51, and FANC genes are susceptible to treatment with PARP inhibitors." (PMID 33660437, 2021). "BRCAness allows for the expansion of the somatic lethality approach to tumors carrying deficiencies in tumor suppressor genes involved in homologous recombination (HR) defective cancers, possessing BRCA1, BRCA2, ATM, ATR, FANC, RAD51, BRIP1, or PALB2 mutations." (PMID 34639169, 2021). "The seminal findings that inhibition of PARP1/2 in BRCA1/BRCA2 mutated cancer cells selectively kills the cancer cells, but leaves the wild type BRCA1/BRCA2 cells intact, helped define a new epoch in personalised medicine that is already transforming patients’ lives." (PMID 34950659, 2021). "Pathogenic variants in BRCA1/2 convey the highest risk of HBOC-associated cancers." (PMID 35008774, 2021). "In the clinics PARP1 inhibitors are successfully used to treat BRCA1 mutated cancers." (PMID 34395585, 2021). "17% of patients had germline protein-truncating variants (PTVs), with biallelic inactivation happening in ~4% of these patiences due to further somatic alteration on top of a germline PTV affecting known cancer-predisposition genes (such as BRCA1, BRCA2, and ATM)." (PMID 34097189, 2021). "Thus, the BRCA1-A complex is likely critical for residual HR activity in cancers with BRCA1 RING domain located mutations." (PMID 34408138, 2021). "In fact, ATM mutations may sensitize cancer cells to platinum-derived drugs, as BRCA1/2 mutations do, whereas their implications in objective responses to hormonal therapy or target-based agents are not well defined." (PMID 34068084, 2021). "Similar treatment responses in cancers with BRCAness and BRCA1/2-mutated tumors have been observed." (PMID 34829741, 2021). "Over time, however, the majority of these BRCA1/2-deficient cancers become resistant." (PMID 34645978, 2021).
cancer (continued). "Targeting the rescue DNA repair pathway in cancer cells carrying DDR deficiencies has been recently shown to be an effective strategy for several cancer types, including BRCA1/2-deficient cancers, where the use of PARP inhibitors (PARPi) is a model example of synthetic lethality." (PMID 34503239, 2021). "Not only may patients and their close relatives become aware of being at increased risk of developing various cancer types, pathogenic BRCA1/2 variants are also treatment targets for poly ADP-ribose polymerase (PARP) inhibitors." (PMID 34660253, 2021). "Increased PD-L1 expression on tumor cells was noted on BRCA-1 mutated cancers only, and this difference may be related to an increased frequency of loss of PTEN function in BRCA-1 as compared to BRCA-2." (PMID 34944679, 2021). "It has been proposed that VEGF, along with Ang-1 and Ang-2, might stimulate the neovascularization in BRCA1/2-mutated cancers." (PMID 35008272, 2021). "BRCA1/2 mutations result in an increased incidence of breast and other cancers." (PMID 34228231, 2021). "However, the combinations exerted a weaker synergistic effect against BRCA1-mutated cancers (e.g., HCC1937 and UWB1.289 cells)." (PMID 33589588, 2021). "Finally, family members responded differently to familial predisposition to cancer: Fact-oriented reactions concerning the familial BRCA1 or BRCA2 mutation were observed in individuals with an own history of cancer." (PMID 34635688, 2021). "The majority of respondents expressed interest in joining a Facebook group that connects cancer survivor with recently diagnosed patients, but the majority of respondents did not express interest in joining a Facebook group that connects cancer survivors with BRCA1/2 mutation carriers." (PMID 35052215, 2021). "Importantly, BRCA1-deficient fibroblasts induced more than 2-fold increase in tumor growth compared to the tumors where control fibroblasts were injected with cancer cells." (PMID 33540843, 2021). "We propose that DDX11 provides a mechanism of replication stress tolerance, which sustains survival of cancers, including BRCA1- and BRCA2-deficient cells, and can be exploited therapeutically through the development of specific inhibitors of DDX11 helicase activity." (PMID 33879618, 2021). "The impact of BRCA mutation status on immune microenvironment in BRCA1/2-associated cancers may represent another potential therapeutic target." (PMID 33540843, 2021). "Although BRCA1- or BRCA2-deficient cancer cells exhibiting defects in homologous recombination (HR deficiency) are hypersensitive to PARP inhibitors through the mechanism of synthetic lethality, acquired resistance to PARP inhibitors was observed in patients with HR deficient HGSOC." (PMID 34063568, 2021). "Indeed, the initial designation of these compounds to BRCA1/BRCA2-mutated cancers already stemmed from the discovery of the synthetic lethal relationship between PARP1/PARP2 inhibition and faulty HR machinery." (PMID 34210965, 2021). "Studies have shown that mammography adds only a small amount of cancer detection to BRCA1 mutation carriers under 40 years old if screening with MRI regularly, while BRCA2 mutation carriers benefit from mammography and MRI, because more cancers are found only through mammography." (PMID 33932123, 2021). "In addition, it was found that BRCA1-deficient SUM149 cancer stem cells are resistant to PARPi, and this resistance is mediated by high levels of RAD51." (PMID 34208492, 2021). "Such heterogeneity of histopathology, genetic alterations and gene expression patterns not only reflects the complexity of mammary tumorigenesis induced by BRCA1 deficiency, but also leads to the difficulty of the efficient treatment on such refractory cancers." (PMID 34815798, 2021). "Blood arsenic level is the marker of cancer risk among BRCA1 mutation carriers." (PMID 34283078, 2021).
cancer (continued). "Consequently, loss-of-function mutations of BRCA1 are one of the best-investigated genetic alterations that predispose to cancer." (PMID 34638302, 2021). "In general, when both parents are carriers of pathogenic BRCA1 mutations, their offspring should have a 75% of chance carrying at least one copy of the pathogenic mutation; hence, the clinical burden of developing cancer is predictable." (PMID 33477375, 2021). "For instance, treating BRCA1/2-mutated tumors with PARP inhibitors is a classic example of taking advantage of a cancer-specific mutation to selectively kill cancer cells by depriving them of a biological mechanism (DNA damage repair) that compensates for this genetic deficiency." (PMID 33562300, 2021). "High-throughput sequencing of tumour genomes revealed that oncogene amplification and BRCA1/2 mutations are mutually exclusive in cancer, however the molecular mechanism underlying this incompatibility remains unknown." (PMID 34389725, 2021). "Compound heterozygosity for deleterious BRCA1 mutations exacerbated cancer disease phenotypes." (PMID 33477375, 2021). "In addition, as many as 4% of these individuals have germline pathogenic mutations in cancer predisposition genes other than BRCA1 and BRCA2 on MGPT (i.e. CHEK2, PALB2, ATM, NBN, PTEN, etc.)." (PMID 33541411, 2021). "Overall, data on cancer risk associated with HRT use in BRCA1/2 mutation carriers are limited." (PMID 33885953, 2021). "With respect to the penetrance in each type of cancer, BRCA1/2 is known to be the strongest factor responsible and therefore, is categorized as a high-risk genetic factor in imparting susceptibility to specific types of cancer." (PMID 35008774, 2021). "Although previous reports have established that PARP inhibitors effectively treat BRCA1-deficient cancers and increase patients’ progression-free survival (PFS), new studies have suggested that HR-deficient cells may also be vulnerable to PARP inhibition." (PMID 34638660, 2021). "The term “genetic responsibility” has been coined in the medical sociology literature, and could be applied to the present study, but has primarily been explored in the context of genetic screening for cancer-associated genes such as BRCA1/BRCA2." (PMID 34831944, 2021). "The optimal clinical management of women with the BRCA1/2 mutations depends on accurate age-specific cancer risk estimates, which can then be used to estimate the absolute risk reduction in preventative strategies and inform decisions regarding the age at which to start surveillance." (PMID 34573353, 2021). "Of note, we also reveal the loss of ARH3 as another potential mechanism through which different types of cancer cells, including BRCA1/2-deficient cancers, could acquire PARPi resistance." (PMID 34019811, 2021). "In the so-called “BRCAness”, BRCA1/2 mutations are the biomarkers to predict cancer patients that could benefit from PARP1 inhibitors as a therapeutic strategy." (PMID 33671256, 2021). "The use of PRS in stratifying cancer risk in carriers of high-risk variants in BRCA1, BRCA2, or other genes, may soon become available for clinical use." (PMID 33762893, 2021). "As FANCI plays a role in FA-HR pathway it may be associated with phenotypically similar cancer families that have implicated BRCA1 and BRCA2." (PMID 34861889, 2021). "Mechanisms governing the initiation of BRCA1-associated cancers remain elusive." (PMID 35008272, 2021). "The prevalent pathogenesis is attributable to inactivating variants of the BRCA1-2 highly penetrant genes, however, other cancer susceptibility genes may also be involved." (PMID 34026625, 2021). "This double-mutation model indicates that some BRCA1/2-mutated cancers could express wt-BRCA1/2-like full-length proteins and, thus, become refractory to a PARP inhibitor monotherapy." (PMID 34948122, 2021). "Germline and somatic BRCA1/2 mutations may define therapeutic targets and refine cancer treatment options." (PMID 34068254, 2021).
cancer (continued). "Thus, previvors and BRCA1/2-mutated patients with cancer face multiple concerns in terms of reproductive challenges that should be separately addressed." (PMID 34503502, 2021). "In 342 cancer cases with BRCA1/2 mutation, which was referred to as HR deficiency, a higher tumor stage was correlated with both higher HRD component scores and a higher HRD combined score, except for the comparison between stage IV and stage III and between stage IV and stage II." (PMID 34869593, 2021). "Knockdown of the histone methyltransferase KMT2B reverses platinum sensitivity of BRCA1 or BRCA2 deficient cancer cells by stabilizing replication forks, while elevated levels of EZH2, another histone methyltransferase, correlates with poor response to platinum therapy." (PMID 34645978, 2021). "However, there is limited information regarding the relationship between dietary trace elements, such as arsenic, and cancer risk among BRCA1 mutation carriers." (PMID 34283078, 2021). "Interestingly, about 60% of the deaths observed in BRCA2-mutation carriers were related to breast and/or other cancers but only 33% of BRCA1-mutation carriers died from breast and/or other cancers." (PMID 34575694, 2021). "The major reason behind this association might be inherited gene mutation such as Breast Cancer Gene 1 (BRCA1) or Breast Cancer Gene 2 (BRCA2) mutations." (PMID 33446123, 2021). "Those groups that used genome-wide CRISPR-Cas9 chemogenetic viability screening identified the Shieldin complex with an elegant experimental set-up in which BRCA1 mutated cancer cell lines or engineered BRCA1 KO cells, were treated with PARPi at a dose with which the majority of cells are killed." (PMID 34950659, 2021). "We hypothesized that mesenchymal stem cells carrying mutations in the BRCA cancer susceptibility genes could enable malignant transformation and tumor progression in BRCA1 carriers." (PMID 33513753, 2021). "Consequently, patients with germline BRCA1/2 mutations are at increased risk for multiple cancer types." (PMID 33391401, 2021). "The pathogenetic role of mutations in BRCA1 and BRCA2, two key components of HR mechanism, has been largely established in several cancers such as breast, ovarian, prostate and PC, and BRCA1/2 germline mutations are among the most common causes of inherited cancer susceptibility." (PMID 34034685, 2021). "In these families, cancer-specific distress and worry play a significant role in the choice to test for BRCA1 mutations as does a greater perceived risk of being a mutation carrier and of developing BC or OC, and the perception that the advantages of BRCA testing outweigh the disadvantages." (PMID 34824606, 2021). "Cancer cells harboring BRCA1/2 mutations are sensitive to PARP inhibitors." (PMID 34919531, 2021). "Loss-of-function mutations in BRCA1/2 lead to a deficiency in the DNA damage repairing pathway called homologous recombination, which could render cancer cells exquisitely vulnerable to the PARP inhibitor (olaparib, OLA)." (PMID 34746227, 2021). "However, a challenging aspect of personalized counseling for BRCA1/2 as well as CHEK2 pathogenic variants is the relatively large range of cancer risk." (PMID 33507482, 2021). "There is also suggestive evidence that BRCA1 pathogenic variants may confer a modest risk EC increase in the absence of tamoxifen exposure, particularly for serous and serous-like subtype cancers." (PMID 33917078, 2021). "PARP inhibitors are being used as anticancer agents in BRCA1/2 mutated cancers." (PMID 34220964, 2021). "This criteria loosening might dilute families with the most aggressive phenotype expression such as VEO cancer in more families with less severe expression or penetrance of the BRCA1/2-related cancer susceptibility syndrome." (PMID 34356116, 2021). "However, in cancer cells deficient for BRCA1/BRCA2, the lesions resulting from PARP trapping cause irreversible damage that kills the cells." (PMID 34950659, 2021).